HGF (hepatocyte growth factor)
Diseases named in the same sentence as HGF in open-access papers (continued):
Sharing a sentence is not in itself a finding about the gene and the disease.
tumor (continued). "Downstream immune-related genes activated by the HGF/c-Met pathway can regulate immune-related pathways, then affect the degree of immune cell infiltration, and thus affect the prognosis of tumor patients." (PMID 35242498, 2022). "In different types of malignant tumors HGF/cMet pathway plays a key role in tumour proliferation, invasion, and metastasis." (PMID 36110531, 2022). "An elevated level of HGF was correlated with an increased probability of advanced pathologic tumor stage (p = 0.01), presence of LVI (p = 0.03), and LN metastasis (p < 0.001)." (PMID 34997350, 2022). "In recent years, there have been many reports on the roles of non-coding RNA (ncRNA) in regulating the HGF/c-Met axis, which are mainly focused on tumor-related studies." (PMID 35370682, 2022). "In this study, we demonstrate that CD44v6+ CSCs not only facilitate cancer stemness properties, such as self-renewal, tumor initiation, promotion of metastasis, and chemotherapy resistance, but also express high levels of the HGF/MET pathway." (PMID 36387747, 2022). "Analysis of tumor specimens from advanced disease found increased expression of TrkB in a subset of samples, all of which had increased expression of HGF and c-MET." (PMID 36034555, 2022). "From a mechanistic point of view, MACC1 induces the activation of the HGF/c-Met axis in multiple tumor entities." (PMID 35740524, 2022). "The HGF/cMET pathway triggers several signaling pathways involved in tumor growth, angiogenesis and metastatic spread." (PMID 36362718, 2022). "HGF in the gastrointestinal tract is responsible for the modulation of cell proliferation, as well as the migration of intestinal epithelial cells, and may, therefore, directly influence the affected tissue, promoting processes associated with rapid tumor growth." (PMID 35328253, 2022). "Other studies have described that the potentiation of HGF/MET activation by ectopic expression of HGF leads to hepatic, renal, and gut abnormalities, whereas MET overexpression confers susceptibility to tumor development." (PMID 35269415, 2022). "Vandetanib inhibits MET phosphorylation and VEGF-1 induced by HGF.Cabozantinib induced phosphorylation of VEFGR2 plays an anti-tumor role." (PMID 36544713, 2022). "c-MET and HGF were found to be expressed in tumor specimens and MB cell lines, and levels of c-MET mRNA correlated with poor clinical outcomes." (PMID 36034555, 2022). "The biological activity of HGF plays a special role in angiogenesis, the adhesion and motility of tumor cells, invasion and the formation of metastases." (PMID 35328253, 2022). "MACC1 promotes tumor development by regulating the HGF/c-Met pathway and microtubule stability and is a key regulator of the c-Met pathway." (PMID 35242498, 2022). "Recent studies have shown that MACC1 is a key regulatory factor in the HGF/c-Met signaling pathway and is a major target for tumor invasion and metastasis." (PMID 35242498, 2022). "TAFs are able to stimulate tumor cell proliferation through the secretion of various growth factors, hormones, and cytokines, including hepatocyte growth factor (HGF), FGFs, SDF-1, and IL-6." (PMID 35741334, 2022). "HGF/c-MET also interacts with the Src/STAT3/FAK/ERK signaling pathway to induce resistance to platinum-based drugs in tumor cells." (PMID 35684449, 2022). "A recent study found that combining abemaciclib, a CDK4/6 inhibitor, with merestinib, a c-MET inhibitor, reduced FOXM1 expression, and significantly inhibited tumor growth in metastatic UM tumors grown in human HGF-knock-in immunocompromised mouse models." (PMID 35954441, 2022).
tumor (continued). "Another important procedure is through the receptor tyrosine kinase Met, which shows that HGF and Met can drive the mobilization and migration of tumor stem cells in tissues." (PMID 35965504, 2022). "Overexpression of HGF has been reported in the tumor microenvironment of 50% of the HNSCC patient samples." (PMID 35081970, 2022). "As one of the cells that can secrete HGF, fibroblasts play an important role in promoting tumor angiogenesis in tumor microenvironment." (PMID 36172142, 2022). "As regards tumor-stroma crosstalk in bone metastasis, the HGF/c-Met receptor axis and TGF-β appear to play relevant roles." (PMID 34572548, 2021). "Combination with PD-L1 checkpoint blockade, HGF remedies the therapeutic limitations of free antibodies, including functional optimization of T cells, and suppression of tumor metastasis." (PMID 34593794, 2021). "We found that HGF induced an increase in tumor size and weight, while curcumin inhibited tumor growth in a concentration-dependent manner." (PMID 34408780, 2021). "Tumor-associated genes on Chr9q such as FANCC, NTRK2, SYK, and NOTCH1 were amplified; amplification of BRAF, EZH2, MET, CDK6 and HGF located on Chr7 were also detected." (PMID 34895266, 2021). "The DS chain of endocan expressed in the capillaries of tumor tissues can bind to and activate HGF to promote tumor cell movement and proliferation." (PMID 34422817, 2021). "HGF/MET has been demonstrated to play an essential role in the ability of a tumour to metastasize by regulating cell motility, migration, proliferation and angiogenesis, and in addition, modulating the tight junction (TJs) cell to cell barrier." (PMID 33917539, 2021). "Emerging evidence indicates that factors from the tumor microenvironment including HGF play a significant role in the regulation of UM cells and their acquired resistance mechanisms to targeted therapies such as MEK inhibition." (PMID 33806615, 2021). "On the other hand, HGF is also able to increase c-Met expression by an autocrine and paracrine manner on epithelial cells and tumor cell lines in vitro." (PMID 34771724, 2021). "We also demonstrated that HGF, rich in the tumor microenvironment in the liver, reduces the effect of CDK4/6 inhibitor in UM." (PMID 33806615, 2021). "Specifically, YAP+ tumor cells increased osteopontin secretion, an important driver of crosstalk between endothelial cells through the hepatocyte growth factor (HGF)/c-Met pathway, promoting tumor cells’ proliferation and survival." (PMID 35008212, 2021). "The neutrophils secrete several inflammatory, immunoregulatory and angiogenic factors, including NE, PR3, CathG, MMPs, VEGF, Bv8 (prokineticin 2), oncostatin M, IL-1β, TGFβ2, BMP2 and HGF, that modulate the tumor microenvironment and affect tumor growth." (PMID 34572138, 2021). "The HGF/Met receptor axis plays many roles in tumor progression, such as proliferation, evasion of apoptosis, invasion, and angiogenesis." (PMID 34572548, 2021). "Aberrant HGF/cMET axis activation, which is closely related to cMET gene polysomy and amplification, promotes tumor development and progression by stimulating the MAPK and other signalling pathways." (PMID 34127734, 2021). "These components are controlled by 10 inputs from the tumour microenvironment (HGF, EGF, ECM stiffness, TGFB, IL6, DELTA, ROS, WNT and the ligands for RPTP and FAT4)." (PMID 34063110, 2021). "MSCs exposed to PDAC cells are activated into CAF-secreting tumor-promoting proteins such as hepatocyte growth factor (HGF), epidermal growth factor (EGF), and interleukin-6 (IL-6)." (PMID 33803229, 2021). "We found it difficult to distinguish between tumor samples and normal samples when using HGF, c-MET, or immune infiltration scores alone." (PMID 34261467, 2021). "Excessive expression of HGF by stromal cells promotes the survival and invasion of tumor cells, but also the polarization of immune microenvironment cells towards immunosuppressive phenotypes." (PMID 34232958, 2021).
tumor (continued). "Existing research reported that tumor-associated neutrophils in CRC produce matrix metalloproteinase 9 vascular endothelial growth factor and hepatocyte growth factor to promote tumor invasion and angiogenesis." (PMID 33747044, 2021). "Abnormal expression of the HGF/c-Met pathway in tumor tissues can promote tumor progression, whereas HGF overexpression in normal tissues can inhibit tumorigenesis." (PMID 34970484, 2021). "HGF has previously been reported to act as a hemangiogenic factor, as well as a mitogenic factor for a variety of tumor cells." (PMID 34885623, 2021). "Metastasis Associated in Colon Cancer-1 (MACC1) has been shown to modulate tumor cell growth and activate invasion and metastasis, mainly by activation of the HGF/MET oncogenic pathway." (PMID 33731131, 2021). "Drug resistance can trigger an increased production of HGF by cancer cells, leading to tumour angiogenesis." (PMID 33526881, 2021). "Dysregulation of the MET/HGF pathway leads to uncontrolled cell proliferation and oncogenesis and is observed in multiple tumour types." (PMID 33526881, 2021). "They concluded that although HGF/c-Met signaling is involved in invasive growth and the antiapoptotic response in most tumor cell types, it can induce apoptosis and prevent malignant transformation in some cases, such as in some transformed cell lines." (PMID 34970484, 2021). "CAFs release stimuli factors, for example, TGF-β superfamily factors (FGF, HGF, etc.)that have the ability for EMT that is associated with E-cadherin loss, enhancing invasiveness of tumor cells for tumor progression." (PMID 34821729, 2021). "The HGF/c-Met receptor pathway plays a role in tumor growth, metastasis, invasion, and angiogenesis." (PMID 34970492, 2021). "P‐Rex1 promotes proliferation and migration of HCC cells and enhances xenograft tumor growth in vivo by activating the HGF/c‐Met signaling pathway." (PMID 34555268, 2021). "We found that the HGF/c-MET pathway affected the tumor microenvironment mainly by interfering with expression levels of other genes." (PMID 34261467, 2021). "ARGX-111 is the first anti-MET agent to be generated capable of killing MET-expressing tumor cells in addition to blocking HGF/MET signaling." (PMID 34200749, 2021). "In cancer, HGF is mainly produced by stromal cells from the tumor microenvironment but also by tumor cells themselves and peripheral blood mononuclear cells (PBMC)." (PMID 34771724, 2021). "HGF/c-Met signaling dysfunction has been reported to be related to cell proliferation, progression and metastatic characteristics of several tumor types, including COAP, which suggests that it has potential value as a novel therapeutic target." (PMID 34261467, 2021). "MACC1 (Metastasis Associated in Colon Cancer 1) is found to regulate the hepatocyte growth factor (HGF)/Met signal pathway, and plays an important role in tumor proliferation, angiogenesis, and metastasis." (PMID 34072650, 2021). "The binding of HGF to its high-affinity receptor, c-Met, can initiate the proliferation, migration, and angiogenesis of various tumors and promote tumor progression." (PMID 34513829, 2021). "The authors found that in the presence of CAF, there was an induction of a tumour invasive phenotype with increased expression of HGF and Tissue inhibitor of metalloproteinases 1 (TIMP-1) and disruption of the EC network, not observed with normal fibroblasts." (PMID 34572836, 2021). "HGF secreted by M2 macrophages and tumor cells activated many growth factor cascades involved in tumorigenesis, such as HGF/c-MET, MAPK/ERK1/2, and PI3K/AKT pathways." (PMID 34722310, 2021). "Combining circulating tumor DNA and protein biomarker-based liquid biopsies demonstrated an increased SN of 64% in a blood test including plasma HGF for early stage PDAC." (PMID 34944713, 2021).
tumor (continued). "Met tyrosine kinase, a receptor for a hepatocyte growth factor (HGF), plays a critical role in tumor growth, metastasis, and drug resistance." (PMID 34848680, 2021). "Early studies found that hepatocyte growth factor (HGF) promotes EMT in tumor cells by altering the expression of E-cadherin on the surface of tumor cells." (PMID 34938806, 2021). "In cancer patients, HGF and c-Met overexpression is related to elevated tumor aggressiveness and a poor prognostic outcome." (PMID 34575943, 2021). "The analysis of 24 paired samples showed a higher expression of HGF in tumors compared with their respective non-tumor surrounding tissue (P=0.015)." (PMID 34037097, 2021). "Stellate cells and myofibroblasts are induced to secrete HGF from tumor cell products, and HGF, in turn, stimulates the invasiveness of tumor cells." (PMID 35008171, 2021). "The combination had an acceptable safety profile and a promising anti-tumor activity by dual inactivation of HGF and EGFR pathways, indicating an active mitigation of cancer progression." (PMID 35087755, 2021). "Such antibody hetero-combinations can also include antibodies against a ligand, for instance vascular endothelial growth factor (VEGF) or HGF, and a receptor, to target both the tumor microenvironment and a tumor-specific receptor." (PMID 34572847, 2021). "C-Met is a receptor tyrosine kinase (RTK) family member, acting as the receptor for hepatocyte growth factor (HGF) and causing tumor genesis." (PMID 34203870, 2021). "NK4, as an HGF antagonist, can inhibit tumor invasion, growth, angiogenesis, and metastasis of tumors in vivo." (PMID 34771620, 2021). "A recent preclinical study demonstrated that the inhibition of both HGF and c-Met combined with gemcitabine improved the reduction of tumour volume and metastasis." (PMID 34336679, 2021). "In a xenograft model, colibactin-producing E. coli indirectly promotes tumor growth by inducing hepatocyte growth factor (HGF)." (PMID 35069592, 2021). "Hepatocyte growth factor (HGF) and its receptor, the Met receptor tyrosine kinase, play important roles in embryonic development, tissue regeneration, and tumor progression." (PMID 34502141, 2021). "The binding of tumor-derived HGF to MET+ neutrophils induced the release of nitric oxide (NO·), which is cytotoxic to cancer cells." (PMID 34572138, 2021). "Targeting HGF by the c-Met inhibitor Tivantinib demonstrated early signs of anti-tumor activity when combined with Gemcitabine in a phase 1 trial of multiple solid tumor patients including breast cancer patients." (PMID 34769066, 2021). "The grade of dysplasia lesions and neoplasm incidence in HGF-Tg mice treated with 4NQO were significantly lower than those in Wt mice (p < 0.05)." (PMID 34970484, 2021). "To further explore the source of HGF in liver environment, we conducted co-culture experiment of tumor cell and cells in liver microenvironment including the hepatic parenchymal cell line L02 cells and human hepatic stellate cell line LX2 cells." (PMID 33995676, 2021). "c-Met is activated by many molecules, including HGF that initiates transcription of a series of gene expressions, leading to tumor cell growth and invasion." (PMID 34050266, 2021). "When c‐Met is upregulated by inhibition of VEGF with Bev, c‐Met forms homodimers to which HGF/SF binds and promotes tumor cell invasion." (PMID 33543833, 2021). "The expression levels of HGF in LUAD were significantly positively correlated with tumor purity, B cells, CD8+ T cells, CD4+ T cells, neutrophils, and dendritic cells." (PMID 34745947, 2021). "Specifically, HGF/Met induces the proliferation and migration of endothelial and tumour cells through RhoA, Rac1, and Cdc42 activation." (PMID 34202487, 2021). "In this study, we have comprehensively provided experimental based evidence to support CYP1A2 as a pivotal tumor suppressor and demonstrated a novel antagonist of HGF/MET signaling in HCC." (PMID 33500715, 2021).
tumor (continued). "This prevents binding of the natural ligand of the Met receptor, HGF (hepatocyte growth factor), which can contribute to tumor survival, growth, angiogenesis, and metastasis under pathologic conditions." (PMID 34917515, 2021). "Resistance is proposed to emerge either from the selection of clones present in treatment-naïve tumours or through MET activation following the increased secretion of the endogenous ligand hepatocyte growth factor (HGF)." (PMID 34069119, 2021). "Recently published data show that higher HGF serum levels negatively correlate with patient survival time and positively with tumor size." (PMID 35008171, 2021). "Hyperactivation of hepatocyte growth factor/c-mesenchymal-epithelial transition factor (HGF/MET) signaling contributes to tumor formation, development, maintenance, and metastasis." (PMID 33500715, 2021). "The tumor number on the tongue surface of HGF-Tg mice was significantly less than that in Wt mice (middle)." (PMID 34970484, 2021). "Sunitinib inhibition of hepatocyte growth factor (HGF) inhibited the upregulation of PD-1 expression in tumor T lymphocytes." (PMID 33859752, 2021). "On the other hand, many DEGs related to tumor development, such as hepatocyte growth factor (HGF) and hepatocyte growth factor receptor (MET), were downregulated." (PMID 33732214, 2021). "In particular, HGF promotes M2 polarization of macrophages, thereby participating in the anti-inflammatory response in various tissues and facilitating tumor progression." (PMID 33658044, 2021). "Foretinib acts by inhibiting HGF-induced MET phosphorylation, VEGF-induced phosphorylation and precludes both HGF-mediated responses of tumor cells and HGF/VEGF-stimulation." (PMID 33918490, 2021). "We found that CTX inhibits tumor-related cytokines, particularly IL-6, IL-8, HGF, TGF-β1, and IGFBP-1." (PMID 34822613, 2021). "Different lines of evidence in cancer patients as well as preclinical tumor models have shown that HGF/c-Met signaling pathway plays an important oncogenic role in lung cancer as well as in PDAC36,37." (PMID 33574356, 2021). "Here, we used molecular approach to demonstrate that SPINT1 serves as a downstream signaling protein of MACC1, participating in tumor genesis and progression through HGF/c‐Met signaling pathway." (PMID 33751856, 2021). "MET is activated upon binding of HGF, leading to downstream activation of the PI3K and MAPK pathways, subsequently causing tumor proliferation, progression, and metastasis." (PMID 34249687, 2021). "From the therapeutic trial, treating these tumor-bearing mice with free PD-L1 antibodies by three doses cannot slow the metastatic speed down, whereas HGF paused the tumor cellular diffusion rapidly." (PMID 34593794, 2021). "The cancer-associated fibroblasts promote tumour invasion with matrix-metalloproteinases 2 and 9, known as MMP2 and MMP9, and the hepatocyte growth factor known as HGF." (PMID 33447887, 2021). "One example of a successful treatment involved inhibiting hepatocyte growth factor (HGF), which is overexpressed in most solid tumors and associated with tumor aggressiveness and poor prognoses." (PMID 34769339, 2021). "In terms of tumor microenvironment, HGF creates an environment favorable for the growth of cancer cells through interaction with cancer cells." (PMID 34683124, 2021). "As such, HGF/c-Met signaling plays an important role in tumor immune evasion and resistance to treatment in the tumor microenvironment." (PMID 34683124, 2021). "Consistent with in vitro cellular results, tumor tissues, and sera collected in HGF group contained highest amounts of IFN-γ." (PMID 34593794, 2021). "HGF/MET signaling is also involved in immune responses in the tumor microenvironment, potentially having a protumor effect." (PMID 34771620, 2021). "This set includes tumor expression of c-Met and serum levels of HGF, IL-6, IL-8, CXCL9, CXCL10 and CXCL11." (PMID 34200459, 2021).